APOB (apolipoprotein B)
Diseases named in the same sentence as APOB in open-access papers (continued):
Sharing a sentence is not in itself a finding about the gene and the disease.
myocardial infarction (continued). "What’s more, ApoB and lipoprotein were usually recognized as vital risk factor of cardiovascular diseases, and positively associated with acute myocardial infarction (AMI) and cerebral infarction (CI)." (PMID 33036576, 2020). "Previous trials had reported that an apoB/apoA-I ratio of ≥ 0.9 is associated with increased risk of myocardial infarction." (PMID 32449038, 2020). "Apolipoprotein B/apolipoprotein A-I ratio was shown to be strongly related to risk of myocardial infarction." (PMID 32449038, 2020). "In the general population, several clinical studies (e.g., AMORIS (Apolipoprotein-related MOrtality RISk) or INTERHEART) have shown that the ApoB/ApoA-I ratio is strongly correlated with cardiovascular events such as myocardial infarction and stroke." (PMID 31915710, 2019). "Glycosylated apolipoprotein B (apoB) is a risk factor for the development of myocardial infarction whereas glycosylated apoB is associated with dysplasia and tumor tissue." (PMID 31140607, 2019). "Prospective risk studies, such as AMORIS, INTERHEART, EPIC-Norfolk study, and ULSAM, indicate that ApoB/ApoA-I ratio is a very useful predictor of risk of myocardial infarction (MI)." (PMID 24949011, 2014). "The INTERHEART Study also reported that ratio of apolipoprotein B/A1 was the most important risk factor for acute myocardial infarction in South Asians." (PMID 18950504, 2008). "In addition, this SNP has been implicated in cardiovascular outcomes: for instance, it was associated with myocardial infarction risk in Chinese populations, likely mediated by hyperlipidemia and higher ApoB levels." (PMID 40773287, 2025). "ApoB is a major protein component of triglyceride-rich lipoproteins and is involved in the transport of cholesterol from liver cells to peripheral cells, promoting cholesterol deposition in arteries and is a known indicator of acute myocardial infarction risk." (PMID 40565139, 2025). "Therefore, ApoB has advantages in assessing the severity of coronary artery stenosis and residual risk in patients with acute myocardial infarction." (PMID 41030852, 2025). "It has been estimated that the level of VLDL-C may account for 46% of the risk of apolipoprotein B (APOB)-related myocardial infarction." (PMID 38216994, 2024). "Additionally, apoB was identified as a more accurate marker for the risk of myocardial infarction than LDL cholesterol." (PMID 38793042, 2024). "Serum ApoB/ApoA1 ratio was also reportedly associated with first myocardial infarction." (PMID 35842724, 2022). "In addition, according to a large comprehensive study (INTERHEART study) the ApoB/ApoA1 ratio was superior for the estimation of the risk of acute myocardial infarction in all ethnic groups, in both sexes and all ages." (PMID 21692678, 2011). "Our results suggest that ApoB appears to be superior to LDL-C in assessing the degree of coronary artery stenosis as well as residual risk in patients after myocardial infarction, and thus lowering ApoB levels could be valuable in further reducing residual cardiovascular risk." (PMID 41030852, 2025). "For myocardial infarction (MI), causality is far less certain, and measured triglyceride concentrations may represent more of a biomarker of risk, with risk mediated by smaller apoB carrying TGRL and remnants arising from incomplete lipolysis of larger TGRLs." (PMID 35681241, 2022). "Elevated apolipoprotein B (apoB) and elevated apoB/apoA-1 ratio increase the risk of myocardial infarction (MI) and stroke, whereas high apoA-1 is protective." (PMID 34851955, 2021). "Prospective risk studies, such as AMORIS, INTERHEART, EPIC-Norfolk study, and ULSAM, indicate that apolipoprotein B/apolipoprotein A-I ratio (ApoB/ApoA-I ratio) is a strong predictor of risk of myocardial infarction (MI)." (PMID 24949011, 2014). "In patients with acute myocardial infarction, ApoB can be considered to guide further intensive treatment." (PMID 41030852, 2025).
myocardial infarction (continued). "Incremental effect of adding ApoB, LDL-C, and TyG indexes to baseline risk models for predicting adverse cardiovascular events after myocardial infarction." (PMID 41030852, 2025). "This aligns with INTERHEART findings of increased myocardial infarction risk when apoB exceeds non‐HDL‐C,26 and ARIC findings that demonstrate higher ASCVD and CHD risk in individuals with low Lp(a) and high apoB." (PMID 40386959, 2025). "The purpose of this study was to investigate the value of ApoB and TyG index in assessing the severity of myocardial infarction and predicting prognosis." (PMID 41030852, 2025). "For the apolipoprotein B and myocardial infarction, the average effect size is estimated as 0.59 with a range of (0.39, 0.90)." (PMID 39006413, 2024). "A multinational case-control investigation on acute myocardial infarction (AMI) patients determined that the ApoB/ApoA1 ratio surpasses all cholesterol ratios in assessing AMI risk across varied gender, age, and race demographics." (PMID 38310324, 2024). "When additionally adjusting for apolipoprotein B, estimates were similar for risk of ischaemic stroke and any ASCVD, attenuated for risk of peripheral artery disease, and strengthened for risk of myocardial infarction." (PMID 37776347, 2023). "The ratio of apolipoprotein B (ApoB) to apolipoprotein AI (ApoAI) is a marker for lipid disturbances as ApoAI is associated with HDL particles and it can predict the risk of myocardial infarction." (PMID 37375611, 2023). "Lastly, apoB proved to be a more powerful predictor for myocardial infarction than LDL-C and triglycerides." (PMID 37629496, 2023). "Data from Indian patients with acute myocardial infarction (AMI) demonstrated that the ApoB/ApoA1 ratio was a better discriminator of coronary artery disease (CAD) risk than other conventional lipid ratios including the ratio of TC/HDL-C and LDL/HDL-C." (PMID 34996506, 2022). "The INTERHEART study has investigated the Apolipoprotein B (ApoB)/ Apolipoprotein A1 (ApoA1) and TC/HDL-C ratios finding an association with acute myocardial infarction (AMI) more frequently in women than in men." (PMID 35268267, 2022). "In patients treated with statins, elevated apoB and non‐HDL cholesterol are associated with the residual risk of all‐cause mortality and myocardial infarction." (PMID 34952989, 2022). "In the INTERHEART study, the apoB/apoA‐I ratio was one of the main predictors of acute myocardial infarction and it was the best predictor of coronary events in the IDEAL study." (PMID 34952989, 2022). "The ability of elevated CRP, CA 19-9 and IL-6 to predict one-year mortality, in terms of ROC statistics, was comparable to the ability of low-density lipoprotein cholesterol and apolipoprotein B to predict myocardial infarction." (PMID 34572824, 2021). "In the next analysis, the ApoB/A1 ratio was examed in complex conditions of cardiovascular and cerebrovascular disease manifestations including previous myocardial infarction, heart failure, and history of cerebrovascular disease." (PMID 31744496, 2019). "The ApoB/ApoA-I ratio represents a strong predictor for coronary artery calcifications, cardiovascular mortality, and myocardial infarction in CKD/ESRD." (PMID 31915710, 2019). "The INTERHEART study suggested that ApoB/apoA1 ratio provided the greatest odds ratio for myocardial infarction (OR = 1.59, 95% CI 1.52–1.64, 3]." (PMID 31744496, 2019). "APOE832/rs405509 located in the putative promoter region has previously been shown to be associated with LDL-related traits (LDL-C, TC, and ApoB), APOE gene expression, myocardial infarction risk, and premature CHD." (PMID 25502880, 2014). "Recently, the multinational INTERHEART study showed that apolipoprotein B (apoB) was a stronger predictor of myocardial infarction than LDL-C, and it is inversely related to physical activity and modifiable with exercise training." (PMID 24102029, 2013).
myocardial infarction (continued). "While power limited one’s ability to detect significance for association of individual loci with myocardial infarction, the authors found significance for loci associated with LDL, HDL, apoB and triglycerides, replicating previous observations." (PMID 24386469, 2013). "Apolipoprotein B is a stronger predictor of myocardial infarction than LDL cholesterol, and it is inversely related to physical activity and modifiable with exercise training." (PMID 24102029, 2013). "In contrast, the INTERHEART case-control study suggested that apoB : apoA-I provides the highest odds ratio for myocardial infarction occurrence compared with LDL-C and TC : HDL-C." (PMID 23125484, 2012). "Studies have shown that apoB and apo A are strongly predictors of myocardial infarction and future cardiovascular events Meanwhile, reduction of HDL-C in opium addicts was significant." (PMID 18980684, 2008). "In previous studies, which were not conducted in Chinese, our study found that ApoB was superior to LDL-C in assessing the severity of myocardial infarction and residual risk." (PMID 41030852, 2025). "The population of acute myocardial infarction was targeted and 712 participants were included in our study to determine the correlation between ApoB and LDL-C levels and coronary severity as well as prognosis, and the metabolic index TyG was also added to our study." (PMID 41030852, 2025). "In a Chinese population study, which focused on myocardial infarction (MI) risk, the G allele of rs676210 (coding for proline at 2739) was identified as the risk variant: Chinese individuals carrying the G allele had higher plasma ApoB levels and an increased risk of MI." (PMID 40773287, 2025). "Therefore, in patients with acute myocardial infarction, ApoB can be considered to guide further intensive treatment." (PMID 41030852, 2025). "In 13,015 statin-treated patients from the Copenhagen General Population Study, serum apolipoprotein–B concentration was shown to be a more accurate marker of both all-cause mortality and myocardial infarction risk than non-HDL cholesterol or LDL-C." (PMID 37841776, 2023). "VLDL cholesterol can explain the increased risk of myocardial infarction associated with elevated levels of apolipoprotein B (apoB), while VLDL triglycerides do not contribute to this risk." (PMID 38288114, 2023). "Both apoB and non-HDL-C appeared equally good at predicting risk of a myocardial infarction but apoB was the more important risk factor of the two when considering total mortality." (PMID 35175548, 2022). "ApoB/ApoA1 ratio was recommended as an accountable risk marker of acute myocardial infarction, unlike the TC/HDLc ratio." (PMID 33725226, 2021). "However, a recent study reported that ApoB was a more accurate marker of myocardial infarction than LDL-C." (PMID 34744709, 2021). "Moreover, the ApoB/ApoA1 ratio is a better predictor of lipoprotein-related risk of cardiovascular disease (CVD) than traditional lipid indexes, and ApoB and ApoA1 are correlated with creatine kinase (CK) in myocardial infarction." (PMID 35069437, 2021). "ApoB was considered a more relevant risk predictor of myocardial infarction than LDL cholesterol in the AMORIS study reports which studied the relationship between apolipoproteins, lipids, and myocardial infarction." (PMID 33725226, 2021). "The results of both AMORIS and INTERHEART studies showed that the apoB/apoA-I ratio was the most powerful predictor of myocardial infarction among all investigated parameters and importantly, like C-reactive protein, was able to detect subjects at higher risk even when LDL-C values were normal." (PMID 32449038, 2020). "As an example, the best predictor of risk of myocardial infarction at the population level in the INTERHEART study was the apolipoprotein (apo) B100/apoA-I ratio, reflecting the correlation between all apoB (atherogenic lipoproteins) and HDL (representing classically anti-atherogenic particles)." (PMID 32872570, 2020).
myocardial infarction (continued). "Moreover, the ApoB/ApoA-I ratio represents a strong predictor for coronary artery calcifications and myocardial infarction in CKD or ESRD." (PMID 31915710, 2019). "Furthermore, both the INTERHEART and the INTERSTROKE studies showed apoB/apoA-I ratio is a strong predictive variable for myocardial infarction as well as stroke." (PMID 26303077, 2015). "However, levels of ApoB and ApoAI or ratio of ApoB : ApoAI are strongest predictor of myocardial infarction and statin is a predictor of slowing progression of coronary atherosclerosis." (PMID 25949827, 2015). "In addition, an apoB/apoA1 ratio of more than 0.7 in men and 0.6 in women was indicated by Walldius as a signal of subsequent occurrence of myocardial infarction." (PMID 24886173, 2014). "A number of prospective studies have shown that high apoB/apoA1 ratio may be a promising marker for predicting the occurrence of future cardiovascular events, such as myocardial infarction and stroke." (PMID 24886173, 2014). "The authors used prospective myocardial infarction case-control studies nested in the Nurses’ Health and Health Professionals Follow-Up Studies to investigate genetic variants associated with myocardial infarction or LDL, HDL, triglycerides, adiponectin and apolipoprotein B (apoB)." (PMID 24386469, 2013). "The results of the AMORIS and INTERHEART studies demonstrated that the apoB : apoA-I ratio was the strongest predictor for myocardial infarction among all investigated variables and most importantly, like CRP, was able to identify subjects at high risk even when LDL-C values were considered normal." (PMID 23125484, 2012). "Importantly, the apoB:apoAI ratio may be a better predictor of myocardial infarction than other ratios or LDLc." (PMID 33596340, 2021). "Therefore, in patients receiving lipid-lowering therapy after myocardial infarction, the use of apoB may be considered to guide further intensive therapy and routine measurement of apoB may be recommended, even if LDL-C levels have been reduced to below standard." (PMID 41030852, 2025). "OR (95% CI) of different levels of ApoB, LDL-C, and TyG and adverse cardiovascular events after myocardial infarction." (PMID 41030852, 2025). "Furthermore, in statin‐treated patients, discordance analysis reveals apoB's superior accuracy over LDL‐C and non‐HDL‐C as a marker for all‐cause mortality risk, and additionally highlights its enhanced accuracy compared to LDL‐C in predicting myocardial infarction risk." (PMID 40386959, 2025). "The correlation coefficients between the level of ApoB as well as the level of LDL-C and the degree of stenosis of coronary artery in myocardial infarction were positively correlated." (PMID 41030852, 2025). "Plotting the ROC curves showed an AUC of 0.634 for ApoB, 0.554 for TyG, and 0.612 for LDL-C.The level of ApoB was a better predictor of the occurrence of major adverse cardiovascular events after myocardial infarction compared with the LDL-C and TyG indices." (PMID 41030852, 2025). "A recent analysis of 13,015 statin-treated patients found elevated ApoB, and not elevated LDL-C, to be associated with increased all-cause mortality and myocardial infarction." (PMID 38674207, 2024). "For example, in the INTERHEART study apoB showed to be a better predictor of myocardial infarction (MI) than LDL-C and non-HDL-C." (PMID 37908502, 2023). "In myocardial infarction, the non-fasting ApoB/ApoA-I ratio has been considered to be a superior biomarker to any other conventional lipid ratio." (PMID 36119695, 2022).
myocardial infarction (continued). "A recent study showed that the levels of TC, LDL, non-HDL and ApoB were significantly higher in patients with myocardial infarction than in the control group, and these lipid levels showed a downward trend with age (27737874)." (PMID 30681575, 2019). "Likewise, the Health Professionals Follow-up Study, which followed 18,225 men for six years, found that apoB was superior to non-HDL-C in predicting nonfatal myocardial infarction." (PMID 40852379, 2025). "Also, myocardial infarction and angina pectoris were more prevalent in the high apoB group; however, there was no information regarding coronary anatomy." (PMID 41374382, 2025). "The early identification of high-risk individuals could lead to effective interventions that prevent heart attacks, strokes, or other CVD events, potentially offsetting the upfront costs of ApoB testing with savings from reduced emergency treatments, hospitalizations, and chronic disease management." (PMID 38535329, 2024). "In the primary prevention cohort, triglycerides, ApoB, and non-HDL-C were each individually related to incident myocardial infarction (MI)." (PMID 38393015, 2024). "Apolipoprotein B (Apo B), total cholesterol (TC), low-density lipoprotein cholesterol (LDL-C), and triglyceride (TG) were still important risk factors for CHD and myocardial infarction (MI) but not for IS." (PMID 33441507, 2022). "Recent studies have shown that apoB has a higher sensitivity and specificity than LDL-C in predicting cardiovascular events, such as myocardial infarction (MI) in both men and women, independent of age." (PMID 34677405, 2021). "A previous study indicated that a high apoB/apoA1 ratio and high non-HDL-C levels are significantly correlated with in-hospital MACEs and out-of-hospital adverse endpoints, including angina, myocardial infarction, new-onset heart failure, stroke, and cardiac death." (PMID 32219140, 2020). "The outcomes were total cholesterol, LDL-C, high-density lipoprotein cholesterol (HDL-C), non-HDL cholesterol, triglyceride (TAG), apolipoprotein B (APOB), high-sensitivity CRP (hs-CRP), major cardiovascular events (MACE), cardiovascular mortality, and myocardial infarction (MI)." (PMID 40792240, 2025).